MIF (macrophage migration inhibitory factor)
Diseases named in the same sentence as MIF in open-access papers (continued):
Sharing a sentence is not in itself a finding about the gene and the disease.
Becker Disease (1 paper, 2019). "We show here a significant enrichment of MIF and related genes in muscle samples from DMD patients, as well as from patients suffering from Becker’s disease and limb-girdle muscular dystrophy type 2B." (PMID 31752120, 2019).
benign prostate hyperplasia (1 paper, 2021). "It is worth to notice that many previous studies have shown increased MIF expression levels associated with benign prostate hyperplasia, induced by chronic conditions." (PMID 34157052, 2021).
bladder transitional cell carcinoma (1 paper, 2024). The most common morphologic subtype of urinary bladder carcinoma (over 90% of cases). "Studies have revealed that the expression of MIF mRNA in bladder transitional cell carcinoma is higher than that in surrounding and healthy tissues." (PMID 38602556, 2024). "According to another study, bladder transition cell carcinoma (BTCC) may develop, invade, metastasize, and recur due to the high expression of MIF and VEGF and their synergistic effect." (PMID 38602556, 2024).
bleeding (1 paper, 2020). "CRP and MIF levels were detected significantly higher in hemophilia patients with acute joint bleeding than patients without acute joint bleeding." (PMID 33023246, 2020).
brain inflammation (1 paper, 2013). "The MIF increases in CSF and serum compartments in highly vs. low exposed children strongly suggest MIF could be a serum biomarker bridge to identify children at risk for brain inflammation." (PMID 24133408, 2013).
Burkitt lymphoma (1 paper, 2007). A rare form of malignant mature B-cell non-Hodgkin lymphoma.
cardiac arrest (1 paper, 2012). Cessation of breathing and/or cardiac function. "In the present study we investigated the response of the pleiotropic inflammatory cytokine macrophage migration inhibitory factor (MIF) to CPR in patients admitted to the hospital after out-of-hospital cardiac arrest (OHCA)." (PMID 22506003, 2012). "To assess the magnitude of MIF release, we compared MIF serum levels of post cardiac arrest patients with those obtained in healthy volunteers and with an aged- and gender-matched group of patients undergoing cardiac surgery with the use of extracorporeal circulation and cardioplegic arrest." (PMID 22506003, 2012). "We therefore investigated MIF serum levels in patients after out-of-hospital cardiac arrest (OHCA)." (PMID 22506003, 2012).
central obesity (1 paper, 2024). "Our present study indicates a positive correlation between plasma MIF levels and AAP-induced enlargement of WHR, suggesting a potential role of MIF in accelerating the development of AAP-induced central obesity." (PMID 38802393, 2024).
cerebrovascular diseases (1 paper, 2023). "In a pilot clinical trial, the increased serum MIF in patients with cerebrovascular diseases following intranasal therapy with M2(LS) CM was associated with a potent clinical response." (PMID 37692837, 2023).
Chlamydial infection (1 paper, 2014). "We also detected an increase of MIF/GIF after chlamydial infection, a pro-inflammatory cytokine promoting the production of tumor necrosis factor (TNF), IFN-γ, IL-1β, IL-2, IL-6 and IL-8." (PMID 25019934, 2014). "Chlamydial infection, irradiation, and the combination of both showed a similar release pattern of a subset of pro-inflammatory cytokines (MIF/GIF, Serpin E1, RANTES, IL-6, IL-8) and chemokines (IL-16, IP-10, ENA-78, MIG, MIP-1α/β) from host cells." (PMID 25019934, 2014).
cholangiocarcinoma (1 paper, 2024). A carcinoma that arises from the intrahepatic biliary tree (intrahepatic cholangiocarcinoma) or from the junction, or adjacent to the junction, of the right and left hepatic ducts (hilar cholangiocarcinoma). "In this study, the enhanced interaction between MIF and CD74 + CD44 in cholangiocarcinoma may inhibit tumor apoptosis and promote angiogenesis by activating the downstream PI3K/Akt signaling pathway." (PMID 38702814, 2024).
chronic asthma (1 paper, 2023). An asthma that is characterized by the development of persistent airway inflammation and recurrent attacks of breathlessness and wheezing, which vary in severity and frequency. "However, it is unclear whether Drp1-mediated mitochondrial fission and its downstream targets mediate MIF-induced proliferation of airway smooth muscle cells (ASMCs) in vitro and airway remodeling in chronic asthma models." (PMID 37674165, 2023).
chronic hepatitis B infection (1 paper, 2025). "Furthermore, higher frequencies of MIF polymorphisms, particularly the MIF-173 G/C variant, have been observed in Iranian patients with chronic HBV, suggesting that certain MIF polymorphisms may influence susceptibility to chronic hepatitis B infection." (PMID 41472252, 2025).
chronic kidney failure (1 paper, 2022). "Our results are in good agreement with data of other groups indicating that high production of MIF is correlated with an increased susceptibility for a large number of inflammatory and metabolic diseases including chronic kidney failure." (PMID 35205271, 2022).
chronic rhinosinusitis (1 paper, 2023). Chronic form of sinusitis. "The MIF pathway significantly influences chronic rhinosinusitis (CRS) by modulating inflammation, tissue remodeling, and mucosal barrier function." (PMID 37745856, 2023).
ciliopathies (1 paper, 2023). "The role of MIF as a transcriptional factor in the regulation of genes related to ciliopathies provides one of the mechanisms of how MIF regulates cilia biogenesis and also suggests a novel therapeutic potential by targeting MIF in the treatment of ciliopathy-associated diseases." (PMID 38052787, 2023). "In addition, PIP4K2a may also regulate ciliopathies through its interaction and phosphorylation of MIF to increase 14-3-3ζ mediated MIF nuclear translocation." (PMID 38052787, 2023). "However, MIF could also be translocated to the nucleus through PIP4k2a/14-3-3 axis to function as a transcriptional factor to regulate the expression of genes related to ciliopathies." (PMID 38052787, 2023).
coagulation abnormalities (1 paper, 2022). "In the present study, the correlations of plasma and urinary MIF levels and prognostic indicators associated with coagulation abnormalities in MN patients were analyzed, and it was found that MIF levels were associated with the hypercoagulable status in MN patients." (PMID 36329091, 2022).
congenital toxoplasmosis (1 paper, 2018). Toxoplasma infection that is present from birth. "Further studies are required to verify if, when congenital toxoplasmosis is studied in a system completely deficient in MIF, the pathology and parasitism will be importantly modified." (PMID 29867817, 2018). "Our group has investigated the role of MIF in congenital toxoplasmosis, since MIF is constitutively expressed during pregnancy and possibly associated with the physiology of gestation." (PMID 29867817, 2018). "Therefore, we have proposed herein the MIF knockout C57BL/6 mice as a study model to investigate MIF function in congenital toxoplasmosis." (PMID 29867817, 2018). "The global absence of MIF was associated with attenuation of pathology in congenital toxoplasmosis, but resulted in female death probably because of uncontrolled infection." (PMID 29867817, 2018). "Therefore, on the basis of the potential role of MIF in the control of T. gondii proliferation and in the putative role of T. gondii in pregnancy physiology, the present study aimed to understand the role of MIF in congenital toxoplasmosis based on an MIF knockout mouse model." (PMID 29867817, 2018). "As the MIF function in congenital toxoplasmosis is not fully elucidated yet, the present study brings new insights for T. gondii infection in the absence of MIF based on pregnant C57BL/6MIF-/- mouse models." (PMID 29867817, 2018). "However, the consequences of a global absence of MIF have not yet been investigated in a model of congenital toxoplasmosis." (PMID 29867817, 2018).
Cutaneous T Cell Lymphoma (1 paper, 2019). "As vorinostat, that is approved for the treatment of Cutaneous T Cell Lymphoma (CTCL) since 2006, has been shown to inhibit MIF production we wondered whether the in vitro chemotherapeutic action of this drug in MYCN transformed NB cell lines could be associated to down-modulation of MIF and DDT." (PMID 31635049, 2019).
delayed hypersensitivity reaction (1 paper, 2010). "Macrophage migration inhibitory factor (MIF) was initially described as a soluble factor identified during the delayed hypersensitivity reaction." (PMID 21152395, 2010).
developmental disabilities (1 paper, 2017). "For example, higher levels of macrophage migration inhibitory factor (MIF) and CXCL8 were observed in plasma and cerebrospinal fluid (CSF) specimens from individuals with ASD compared with those from typically developing (TD) controls and subjects with other developmental disabilities." (PMID 28167942, 2017).
dilated cardiomyopathy (1 paper, 2025). Cardiomyopathy which is characterized by dilation and contractile dysfunction of the left and right ventricles. "Immune cells and MIF are implicated in many of these conditions and may affect progression of inflammatory cardiomyopathy (ICM) to myocardial remodeling and dilated cardiomyopathy (DCM)." (PMID 40092999, 2025).
E. coli infections (1 paper, 2019). "The response of HBMECs to meningitic and non-meningitic E. coli infections highlighted the role for macrophage migration inhibitory factor (MIF) during infection." (PMID 31671896, 2019).
edema (1 paper, 2013). An abnormal accumulation of fluid beneath the skin, or in one or more cavities of the body. "This would suggest that despite significant vascular leak/pulmonary edema, increased release/secretion of MIF itself and/or some other factor/protein was possibly contributing to the protective response in hyperoxia." (PMID 23637753, 2013).
empyema (1 paper, 2021). An accumulation of pus in a body cavity, usually the pleural space. "Interesting, the pleural levels of MIF and IL-1β were significantly higher in empyema compared with CPPE." (PMID 33469074, 2021). "In conclusion, our results identify elevated MIF and MIP-3α as novel biomarkers for PPE diagnosis, particularly in patients with CPPE/empyema." (PMID 33469074, 2021). "The pleural levels of four cytokines (MIF, MIP-3α, IL-1β, ENA-78) were highest and significantly increased in CPPE/empyema compared with those in other etiologies." (PMID 33469074, 2021). "Among the six different types of effusions, the mean concentrations of MIF, MIP-3α, IL-1β, and ENA-78 were highest and most significantly increased in CPPE/empyema relative to those in effusions of other etiologies, including UPPE, other exudates, transudates, and MPE." (PMID 33469074, 2021). "In conclusion, our results show that elevated MIF and MIP-3α may be used as novel biomarkers for PPE diagnosis, particularly in patients with CPPE/empyema; the findings indicate that dysregulated cytokine expression may provide clues about the pathogenesis of pleural infection." (PMID 33469074, 2021). "We further identified seven additional cytokines (MIF, MIP-3α, ENA-78, Groβ, Groα, MCP3, and fractalkine) that have not been reported to increase significantly in CPPE/empyema compared to UPPE." (PMID 33469074, 2021). "The possibility that increased pleural levels of MIF and MIP-3α may serve as biomarkers for distinguishing PPE, especially CPPE/empyema, from noninfectious PE was first explored in this study." (PMID 33469074, 2021).
fungal keratitis (1 paper, 2019). "Further study to confirm whether miR-451a targets MIF in a specific cell type and how this regulation modulates the pathogenesis of fungal keratitis will provide more insight into the role of miR-451a in fungal keratitis and its potential as a therapeutic target." (PMID 31533211, 2019).
gallbladder adenocarcinoma (1 paper, 2015). A carcinoma that arises from glandular epithelial cells of the gall bladder. "In this study, tissue microarray-based immunohistochemical staining revealed overexpression of MIF in more than 72 % of the gallbladder adenocarcinoma cases." (PMID 26530123, 2015). "The expression of macrophage migration inhibitory factor was analysed in gallbladder adenocarcinoma tissues using immunohistochemistry." (PMID 26530123, 2015). "A Chi-square test clearly indicated a significant overexpression of MIF in gallbladder adenocarcinoma cases (p-value <0.05) at a confidence level greater than 95 %." (PMID 26530123, 2015). "Having found that MIF is overexpressed in gallbladder adenocarcinoma tissue, we sought to investigate the role of MIF in GBC." (PMID 26530123, 2015). "Immunohistochemical labeling of tumor tissue microarrays for MIF expression revealed that it was overexpressed in 21 of 29 gallbladder adenocarcinoma cases." (PMID 26530123, 2015).
gastric polyps (1 paper, 2024). "Through bidirectional investigation approach, it could be inferred that certain biomarkers are more likely to be found later in the course of the illness, like bNGF, FGFBasic, GCSF, GROa, IL-13, IL-5, IL-7, MCSF, SCGFb in gastric polyps, and CTACK, MIF in colonic polyps." (PMID 39439893, 2024).
gastric tumor (1 paper, 2014). "Gastric tumor-derived fibroblasts produced approximately 600 pg/ml of MIF while normal tissue-derived fibroblasts produced approximately 70 pg/ml of MIF." (PMID 24887129, 2014).
gastrointestinal carcinoma (1 paper, 2014). "In addition, we found that tumor associated MF were a source of elevated MIF production when compared to MIF production from normal tissue associated MF and that conditioned media from tumor associated MF increased gastrointestinal carcinoma proliferation." (PMID 24887129, 2014). "Perhaps most intriguingly, however, was the demonstration that chronic MIF treatment led to changes in pro-tumorigenic signaling pathways in gastrointestinal carcinoma cells as well as MET in cells expressing fibroblast markers." (PMID 24887129, 2014).
giardiasis (1 paper, 2026). An infection of the small intestine caused by the flagellated protozoan giardia lamblia. "However, the role of G. duodenalis MIF (GdMIF) in giardiasis remains to be elucidated." (PMID 41628255, 2026).
heart injury (1 paper, 2022). Injury to the heart. "It has been reported that MIF expression is enhanced after ischemic heart injury in animal models." (PMID 36104681, 2022).
hemangiosarcomas (1 paper, 2011). "Mice null for the pro-inflammatory cytokine macrophage migration inhibitory factor (MIF-KO) showed less evidence of hemangiosarcomas compared with WT controls." (PMID 21115536, 2011).
hemophilia (1 paper, 2020). Hemophilia is a genetic disorder characterized by spontaneous hemorrhage or prolonged bleeding due to factor VIII or IX deficiency. "This study has demonstrated that serum CRP and MIF levels increases in acute bleeding period regardless of the presence of previous joint damage in children with severe hemophilia and that CRP elevation may be a useful and rapid marker for acute bleeding in severe hemophilia A patients." (PMID 33023246, 2020).
hemorrhage (1 paper, 2022). Loss of blood from the vascular compartment to the exterior or into nonvascular body space as a result of rupture or severance of the blood vessels. "In the present study, we examined temporal changes of MIF levels in serum, CSF, and MD during the first 3 weeks after hemorrhage and their relation to disease progression and outcome." (PMID 36712451, 2022). "MIF levels were measured in serum, CSF and MD obtained from 30 aSAH patients during early (EPd1−4), critical (CPd5−15) and late (LPd16−21) phase after hemorrhage." (PMID 36712451, 2022).
Hepatic failure (1 paper, 2010). "It was reported that liver I/R injury causes the expression of MIF, and anti-MIF antibody attenuates hepatic injury in a mice endotoxin-induced fatal hepatic failure model." (PMID 21197406, 2010).
hepatoblastoma (1 paper, 2013). Hepatoblastoma (HB) is a malignant hepatic tumor and is the most common pediatric liver cancer. "Through intracellular TG measurement and Oil Red O staining, we demonstrated that MIF administration inhibited chemically induced lipid accumulation in mice liver and human hepatoblastoma cell lines." (PMID 23823021, 2013).
hippocampal atrophy (1 paper, 2024). "Additionally, several linear mixed-effects models were performed to investigate the association between CSF MIF and hippocampal atrophy for the CU and CI groups separately." (PMID 39877076, 2024).
Hyperbilirubinemia (1 paper, 2016). An increased amount of bilirubin in the blood. "MIF deficiency partially alleviated iron accumulation in tissues, hyperbilirubinemia, hypoalbuminemia and defective coagulation, most likely because T. congolense-infected Mif-/- mice exhibited reduced erythrophagocytosis combined with reduced hemodilution and liver injury." (PMID 27632207, 2016).
Hypercholesterolemia (1 paper, 2022). An increased concentration of cholesterol in the blood. "When genotype frequencies were analyzed according to the presence of the Hypercholesterolemia of 22 ESRD-affected patients, 9 were positive for C allele bearing genotype of MIF rs755622 with an increase of genotype frequencies with respect to hypercholesterolemic controls." (PMID 35205271, 2022).
hypertrophic cardiomyopathy (1 paper, 2024). A condition in which the myocardium is hypertrophied without an obvious cause. "We also detected the expression of hypertrophic cardiomyopathy markers such as atrial natriuretic peptide (ANP), B‐type natriuretic peptide (BNP), β‐myosin heavy polypeptide (MHC), and MIF." (PMID 38924383, 2024). "We found that all the hypertrophic cardiomyopathy markers (ANP, BNP, and β‐MHC) were significantly increased in TAC‐treated mice and overexpression of MIF in TAC‐treated mice attenuated the increases of these markers." (PMID 38924383, 2024).
hypoparathyroidism (1 paper, 2021). Hypoparathyroidism is an endocrine disorder in which the parathyroid glands in the neck do not produce enough parathyroid hormone (PTH). "MIF levels were significantly associated with postoperative transient recurrent laryngeal nerve injury and hypoparathyroidism." (PMID 34575145, 2021). "The preoperative serum MIF levels showed a significant correlation with postoperative hypoparathyroidism [29.24 (10.76–50.82) vs. 4.37 (2.77–47.53), p < 0.001]." (PMID 34575145, 2021). "In the current study, we demonstrated that increased preoperative serum MIF levels were significantly associated with surgical complications, including transient RLN injury and hypoparathyroidism." (PMID 34575145, 2021). "Our study suggests that preoperative serum MIF level is positively associated with longer operation time, more blood loss and higher TDS score, and postoperative complications, including transient RLN injury and hypoparathyroidism in patients." (PMID 34575145, 2021). "In addition, increased preoperative serum MIF levels were associated with increased TDS score, operation time, blood loss, and postoperative complications, including transient RLN injury and hypoparathyroidism." (PMID 34575145, 2021). "In addition, increased preoperative serum MIF levels were associated with higher TDS scores, operation time, blood loss, and postoperative complications, including transient RLN injury and hypoparathyroidism." (PMID 34575145, 2021).
hypopharyngeal carcinoma (1 paper, 2025). Carcinoma, predominantly squamous cell, arising from the epithelial cells of the hypopharynx. "Current investigations into MIF as a biomarker in hypopharyngeal carcinoma remain limited, highlighting a significant scarce in the existing research and so need more research and investigations." (PMID 41159021, 2025).